LRRC57 (leucine rich repeat containing 57)
Synonyms: FLJ36812
Tractability: PROTAC: ubiquitination databases record sites on it; its protein half-life has been measured.
Gene: Protein-coding gene on chromosome 15 (42,537,820 to 42,548,802, reverse strand). Ensembl gene ENSG00000180979.
Subcellular location: Membrane
Subcellular location (Human Protein Atlas): Cytosol; Mitochondria
Gene Ontology:
Cellular component: extracellular exosome; membrane
Genetic constraint (gnomAD): Loss-of-function variants: 11 observed, 19.26 expected, observed/expected ratio (o/e) 0.57, 90% interval 0.36 to 0.94. The upper end of that interval is the gene's LOEUF score, 0.94, which puts it in group 4 of 6, group 1 being the genes least tolerant of losing a copy. Missense variants: 221 observed, 276.73 expected, observed/expected ratio (o/e) 0.8, 90% interval 0.71 to 0.89. Synonymous variants: 102 observed, 115.64 expected, observed/expected ratio (o/e) 0.88, 90% interval 0.75 to 1.04.
Homologues: Orthologues: chimpanzee LRRC57 (100% identical), macaque LRRC57 (99% identical), rabbit LRRC57 (96% identical), mouse Lrrc57 (95% identical), rat Lrrc57 (95% identical), dog LRRC57 (95% identical), pig LRRC57 (95% identical), guinea pig LRRC57 (90% identical), tropical clawed frog lrrc57 (73% identical), zebrafish lrrc57 (70% identical), Drosophila melanogaster CG3040 (49% identical).
Diseases named in the same sentence as LRRC57 in open-access papers:
LRRC57 is named in the same sentence as 2 diseases in open-access papers, as found by Europe PMC text mining. Sharing a sentence is not in itself a finding about the gene and the disease. The quoted sentences say what the papers report.
bipolar disorder (2 papers, 2018 to 2023). A disorder of the brain that causes unusual shifts in mood, energy, activity levels and the ability to carry out day-to-day tasks. "For example, leucine-rich repeat containing genes (which include LRRC37A, implicated in neuroticism, and LRRC57, implicated in bipolar disorder) are known to be key organizers of excitatory and inhibitory synapse formation." (PMID 30419947, 2018). "Increased expression of the LRRC57 gene, encoding Leucine Rich Repeat Containing 57, was associated with bipolar disorder (P-SMR = 3.07 × 10− 5)." (PMID 30419947, 2018).
LRRC57 also shares sentences with these, for which no sentence is quoted: schizophrenia (1 paper).